CXCL8 (C-X-C motif chemokine ligand 8)
Diseases named in the same sentence as CXCL8 in open-access papers (continued):
Sharing a sentence is not in itself a finding about the gene and the disease.
gastric cancer (continued). "In addition, the CXCL8/PI3K/PKB signaling pathway is also over-activated in gastric cancer, ovarian cancer, colorectal cancer, which can promote cell proliferation, metabolic reprogramming, regulate angiogenesis, induce EMT, and improve the infiltration ability of cancer cells." (PMID 37377954, 2023). "In gastric cancer, through inducing macrophages and PD-L1 to participate in the immunosuppression of the tumor microenvironment, CXCL8 inhibitors could trigger the anti-tumor response, which could provide potential therapeutic effects for gastric cancer patients." (PMID 34729112, 2021). "Gastric cancer tumors show a higher expression of CXCL1 and CXCL8 than healthy gastric tissue; the expression of both of these chemokines is highest in diffuse-type gastric carcinoma." (PMID 37408240, 2023). "Since noticing the potential role of CXCL8, CXCR1, and CXCR2, more scientists have explored their relationship with gastric cancer." (PMID 36831112, 2023). "The promoter region of the CXC ligand-8 (CXCL8) gene contains KLF4 binding sites, and the inactivation of KLF4 in gastric cancer tissues resulted in significant upregulation of the CXCL8 expression." (PMID 36761967, 2023). "Mast cells promote the development of gastric cancer by releasing angiogenic (VEGF-A, CXCL8, MMP-9) and lymphangiogenic components (VEGF-C, VEGF-F)." (PMID 36923439, 2023). "MCs exert a pro-tumorigenic role in gastric cancer through the release of angiogenic (VEGF-A, CXCL8, MMP-9) and lymphangiogenic factors (VEGF-C and VEGF-F)." (PMID 35626257, 2022). "Gastric cancer derived mesenchymal cells secrete IL-6 and IL-8 (CXCL8) through JAK2/STAT3 signaling pathway and induce polarization of gastric cancer M2-macrophages." (PMID 35479325, 2022). "Further investigation performed in gastric cancer indicates that TAMs can induce themselves increasing the expression of PD-L1 and decrease CD8(+) T cells infiltration by secreting CXCL8." (PMID 35372515, 2022). "Importantly, the authors provided evidence that tumor-associated macrophages-derived CXCL8 determines immune evasion through autonomous PD-L1 expression in gastric cancer, suggesting that it may be a promising strategy to block the CXCL8 pathway to increase anti-tumor immunity in gastric cancer." (PMID 34729112, 2021). "JNK activation promoted VEGF-A, CXCL1, CXCL5, IL-8/CXCL8, and MMP-1 through inflammatory cytokine IL-1α in human gastric cancer cell lines." (PMID 34063627, 2021). "Gastric cancer extracellular vesicles transfer various miRNAs and induce chemokines such as CXCL1 and CXCL8 expression in CAFs." (PMID 35011369, 2021). "For instance, in gastric cancer, EVs containing miR155, miR193b, and miR210 prime CAFs to secrete inflammatory chemokines, such as CXC ligand (CXCL)-1 and CXCL-8, through the activation of the Janus kinase (JAK)/STAT and NF-κB signaling pathways." (PMID 33553157, 2020). "The consensus-expressed PNI gene signature (CXCL8 and MMP9) in gastric cancer is identified on the basis of meta-analyzed GEO datasets." (PMID 31681401, 2019). "In this research, consensus-expressed CXCL8 and MMP9 are identified in gastric cancer, and a higher coexpression can predict poor disease-free survival." (PMID 31681401, 2019). "Mast cells exert a protumorigenic role in gastric cancer through the release of angiogenic (VEGF-A, CXCL8, MMP-9) and lymphangiogenic factors (VEGF-C and VEGF-F)." (PMID 31035644, 2019). "Based on these findings, we propose that GLO1 mediates gastric cancer cell migration and invasion at least partially mediated through activation of CXCL1, CXCL8, and VEGF." (PMID 22479608, 2012). "In our experiments, levels of both HIF-1α and NF-κB were reduced in nuclei upon GLO1 silencing in gastric cancer cell lines, along with downstream target genes (VEGF, CXCL1, CXCL8, MMPs)." (PMID 22479608, 2012).
gastric cancer (continued). "In addition, CXCL8 can enhance the activity of MMPs and promote the degradation of ECM by MMPs, which is beneficial for the invasion of gastric cancer cells." (PMID 37377954, 2023). "As a pro-inflammation chemokine, CXCL8 participates in the development of many diseases; for example, CXCL8 induces PD-L1 expression in macrophages to inhibit the functions of CD8+ T cells and promote an immunosuppressive microenvironment in gastric cancer." (PMID 35303800, 2022). "All these indicated that the CXCL8 and MMP9 coactivated bioprocess might be the consistent phenotype involved in PNI-related gastric cancer." (PMID 31681401, 2019). "The higher expression levels of both CXCL8 and MMP9 in a gastric cancer sample were also confirmed in the TCGA data when compared with a normal sample analyzed with GEPIA, and it was further found that the correlation between CXCL8 and MMP9 expressions was R = 0.49 (p = 0)." (PMID 31681401, 2019). "Further, gastric cancer cells secrete extracellular vesicles that alter the expression of various genes in different cells in the tumor niche, for example extracellular vesicles that contain miR-155, miR-193b and miR-210, inducing the expression of chemokines CXCL1 and CXCL8 in fibroblasts." (PMID 37408240, 2023). "It must be mentioned that CXCL8 can regulate the development and progression of gastric cancer in an inflammatory-chemotaxis–independent manner, although the CXCL8 target fails to explain the signaling effects of other CXC chemokines that emerged in some preclinical trials." (PMID 31681401, 2019).
lung carcinoma (306 papers, 2004 to 2026). "This study evaluated the effects of CXCR1/2 antagonism by G31P, a CXC motif chemokine ligand 8 (CXCL8)-mutated peptide, alone or in combination with gefitinib, on lung cancer growth and chemotherapy-induced pulmonary inflammation." (PMID 41425704, 2025). "In lung cancer and colorectal cancer, high levels of CXCL8 expression suggested an increased risk of cancer and unfavorable prognosis." (PMID 28883082, 2017). "We found that EGF was involved in the development of the lung cancer inflammatory microenvironment through the over-production of CXCL8 associated with the activation of EGFR pathway." (PMID 24629040, 2014). "CXCL8 is a potent chemoattractant for neutrophils and myeloid-derived suppressor cells and is linked with worse prognosis in multiple cancer types, including lung cancer." (PMID 37192000, 2023). "C-X-C motif chemokine ligand 8 (CXCL8) is a major mediator of the inflammatory response that is significantly associated with and susceptible to hypertension, and diabetes has a positive correlation with obesity and lung cancer." (PMID 36685671, 2023). "CXCL10 and CXCL11 may also be useful diagnostic biomarkers in early-stage NSCLC, while CXCL8 levels may be a useful predictor of future lung cancer risk." (PMID 36164329, 2022). "Similarly CXCL8/IL-8, which is expressed in benign and malignant PE is associated with the mesenchymal phenotype in lung cancer." (PMID 31741710, 2019). "It is associated with C-X-C motif chemokine ligand 8 (CXCL8)-mediated neutrophil infiltration, CD68-positive macrophages in lung cancer, and M2 macrophage polarization in triple-negative breast cancer." (PMID 40722952, 2025). "Bioinformatic analysis via the TCGA database revealed that the expression levels of JUN and CXCL8 are higher in stage IV lung cancer, suggesting a potential positive correlation between their expression and disease progression." (PMID 39990658, 2025). "This study systematically evaluated the potential causal relationship between three key inflammatory factors (CDKL1, CXCL8 and TGFB1) and the risk of non‐small cell lung cancer (NSCLC) using Mendelian randomisation (MR) methodology." (PMID 40682474, 2025). "We investigated the relationships between CXCL8 expression, lung cancer progression, and smoking history using The Cancer Genome Atlas (TCGA) database." (PMID 39519144, 2024). "Our study only showed that CXCL8 expression, which is related to lung cancer prognosis, was increased by 1,2-NQ in vitro and correlated with smoking history in the TCGA database." (PMID 39519144, 2024). "CXCL8 was also increased in serum samples from lung cancer patients with bone metastases and was involved in lung cancer-induced osteoclastogenesis in vitro." (PMID 37025604, 2023). "A study observed that the levels of CXCL1, CXCL2, CXCL5, CXCL7, and CXCL8 were higher in lung cancer compared to multiple other cancer types (breast, colorectal, esophageal, head and neck, and liver cancer)." (PMID 36612163, 2022). "In fact, PD-L1 expression is induced after exposure to interferon-γ (IFN-γ) released by T effector cells, as well as after other signals such as TNF-α, VEGF, and CXCL8, ultimately promoting lung cancer progression." (PMID 32630659, 2020). "We are inspired by these studies and conducted relevant mechanism explorations to prove the relationship between DACH1 and CXCL8 in lung cancer." (PMID 29636079, 2018). "In this study, high expression of CXCL8 was detected in NSCLC both at mRNA and protein levels and was also remarkably associated with poor prognosis of lung cancer patients." (PMID 29636079, 2018). "Lung cancer cell lines were shown to express increased CXCL8 which promotes tumor growth, angiogenesis, and invasion." (PMID 29636079, 2018). "We also found that EGFR–PI3K–Akt–Erk pathway was involved in the development of lung cancer inflammatory microenvironment by the hyper-production of CXCL8, responsible for leukocyte recruitment, cancer proliferation, and angiogenesis." (PMID 24629040, 2014).
lung carcinoma (continued). "The present study was designed to investigate the possible interrelation between BTC and CXCL8 in human lung cancer cells (A549) and demonstrated the mechanisms of intracellular signals in the regulation of both functions." (PMID 24629040, 2014). "The present study furthermore investigated the involvement of EGFR–PI3K–Akt–Erk activation in CXCL8 production induced by BTC with consequences on lung cancer cell proliferation and movement." (PMID 24629040, 2014). "Higher levels of CXCL8 have been detected by IHC in lung cancer tissue samples when compared with normal, and in our samples levels of CXCL8 mRNA were elevated in 37.8% (14/37) samples." (PMID 21298036, 2011). "CXCL8 is a mediator of angiogenesis in lung cancer and correlates with angiogenesis, tumour progression and poor survival in NSCLC." (PMID 20429924, 2010). "Zhu found that cell proliferation was significantly reduced by anti-CXCR1 antibody but not by anti-CXCR2 antibody and concluded that the mitogenic function of CXCL8 in lung cancer is mediated mainly by CXCR1 receptor." (PMID 20429924, 2010). "CXCL8 also plays a role in the proliferation, invasion, and migration of lung cancer cells." (PMID 39962077, 2025). "Taken together, our data showed that cigarette smoking, along with 1,2-NQ exposure, may aggravate lung cancer by promoting CXCL8 expression." (PMID 39519144, 2024). "We also showed that high CXCL8 mRNA levels were positively correlated with lung cancer malignancy." (PMID 39519144, 2024). "Although certain genetic variations in CXCL8 have been linked to more severe pain in lung cancer patients, similar associations between CXCL8 variations and chronic pain disorders have not yet been investigated." (PMID 39201416, 2024). "We found that CXCL8 expression was positively correlated with lung cancer stage." (PMID 39519144, 2024). "Although further studies are needed to determine the contribution of 1,2-NQ to CXCL8 expression, our data suggest that environmental electrophiles such as 1,2-NQ may contribute, at least in part, to the exacerbation of lung cancer." (PMID 39519144, 2024). "Through RNA-seq analysis, the effects of propofol and sevoflurane during lung cancer resection were different, mainly in inflammatory-related pathways, which might be possibly by targeting CXCL8." (PMID 36647133, 2023). "Furthermore, CXCL8 which promotes angiogenesis and tumor progression was increased by 40-fold in lung cancer patients as compared to healthy controls." (PMID 37580655, 2023). "In lung cancer development, CXCL8 has been known to be an essential growth factor." (PMID 36831112, 2023). "Thus, it indicated that serum chemotatic factors like CXCL8 have the possibility of differential diagnosis of lung cancer such as NSCLC." (PMID 37393391, 2023). "Similarly, higher elevated levels of CXCL8 have been observed in the serum and tumor tissues in patients with Kras mutant-pancreatic and lung cancer." (PMID 35127700, 2021). "Increased CXCL8 is detected in lung cancer, especially in NSCLC cell lines." (PMID 29636079, 2018). "It suggested the specificity of correlation between DACH1 and CXCL8 in lung cancer." (PMID 29636079, 2018). "Our data indicated that CXCL8 production from lung cancer cells could be initiated by an autocrine mechanism or external sources of BTC through the EGFR–PI3K–Akt–Erk pathway to the formation of inflammatory microenvironment." (PMID 24629040, 2014). "A positive correlation of BTC and CXCL8 expression in lung cancer was observed." (PMID 24629040, 2014). "The present study provided the further evidence that both BTC and CXCL8 could be over-produced directly by lung cancer cell per se in the inflammatory condition and/or stimuli like LPS." (PMID 24629040, 2014). "Thus, our data indicate that the signal pathway of BTC-EGFR–PI3K–Akt–Erk-CXCL8 plays an important role in the inflammatory microenvironment in lung cancer, as a novel therapeutic approach to lung cancer." (PMID 24629040, 2014).
lung carcinoma (continued). "In summary, the present study demonstrated that LPS increased the over-production of BTC and CXCL8 from human lung cancer cells, which could be blocked by anti-BTC neutralizing antibody." (PMID 24629040, 2014). "Therefore, we investigated whether 1,2-NQ-induced CXCL8 expression promotes lung cancer cell growth." (PMID 39519144, 2024). "CXCL8 showed increased expression in S cancer samples but decreased expression in P cancer samples, which may suggest that cancer cells respond differently to P and S during lung cancer resection." (PMID 36647133, 2023). "We found that the signal pathway of BTC-EGFR-PI3K axis may play the crucial and dependent role in the mechanism of CXCL8 production of lung cancer cells, evidenced by the finding that the over-production of CXCL8 by BTC was fully prevented by PI3K and EGFR inhibitors." (PMID 24629040, 2014). "For example, it upregulates CXCL8 and IL6 in ovarian cancer patients and CXCL10 expression in lung cancer cells." (PMID 39759512, 2024). "The mRNA expression of CXCL-8, CXCR1 was inhibited in a study comparing lung cancer cells with a control group in terms of migration and invasion during epithelial to mesenchymal transition." (PMID 36926328, 2023). "Reduced mRNA expressions of urokinase plasminogen activator (uPA) and inhibited mRNA expression of CXCL-8, CXCR1, ß-catenin connection to migration and invasion of EMT in lung cancer cells." (PMID 36926328, 2023). "Anakinra has also been shown to reduce the levels of CXCL8 and number of TAM as well as reducing lymph node metastasis in a murine model of lung cancer." (PMID 35047989, 2021). "The upregulated genes included CYP4F3, IL1RL1, PTGS2, and CXCL8, which are related to inflammation; HKDC1, MYEF2 and CYP1A1, which are related to hepatocarcinoma or lung carcinoma; and SLC7A11 and NEFM, which are related to neuronal damage." (PMID 33247188, 2020). "We have preliminary evidence that two different bathes of A009, sharing HyT as the most abundant polyphenols, reduce the production of VEGF and CXCL8 in A549 and H1650 lung cancer cells, and the production of CCL2 in A549 lung cancer cells." (PMID 32224910, 2020). "IL-8, also known as CXCL8, has been reported as a marker for poor outcomes in hormone-dependent breast cancer, colorectal cancer, and lung cancer." (PMID 33680949, 2020). "The effect of S1P on IL-8/CXCL8 production has been demonstrated in normal epithelial virus-transformed BEAS-2B cell line, A549 lung carcinoma line and human airway smooth muscle." (PMID 29467963, 2018). "In agreement with previous result, DACH1 transcriptionally downregulates the CXCL8 in NSCLC, and an inverse relationship between CXCL8 and DACH1 was identified in lung cancer cell lines and tumor tissues." (PMID 29636079, 2018). "Based on this observation, we conducted relevance analysis between CXCL8 and DACH1 at mRNA level in lung cancer tissues and cell lines." (PMID 29636079, 2018). "Meanwhile, CXCL8 promotes proliferation and induces epithelial-mesenchymal transition (EMT) in lung cancer cells." (PMID 29636079, 2018). "For lung cancer, high intra-tumoral concentrations of CXCR2 ligands (CXCL1, CXCL5, and CXCL8) and type 2 cytokines IL-4, IL-5, IL-10, and IL-13 have been reported for non-small cell lung cancer." (PMID 26231039, 2015). "In this study, we examined the production of pro-angiogenic factors, VEGF, IL-8/CXCL8, and CXCL5, to determine the effects of IL-27 on angiogenesis in human lung cancer." (PMID 24274066, 2013). "The induction of CXCL8 was significant in HBEC4 and SKMES-1 (p<0.05), as was the increase in CXCR1 and CXCR2 in both the lung cancer cell lines (A549 - p<0.05, SKMES-1 – p<0.01) and CXCR1 in HBEC4 (p<0.05)." (PMID 21298036, 2011). "Using the histone deacetylase inhibitor (HDACi), Trichostatin A (TSA), an induction of CXCL8 and CXCR1/2 in both the normal (HBEC4) and lung cancer cell lines (A549 and SKMES-1), with a concomitant decrease in CXCL1–3 (SKMES-1, p<0.05) was observed." (PMID 21298036, 2011).
lung carcinoma (continued). "Moreover, doxorubicin upregulates CXCL8 and TNF in lung cancer cells and IL12-induced IFNG in xenografted breast cancer." (PMID 39759512, 2024). "It is not only CXCL8 enabling the self-renewal and propagation of CSC-like cells in lung cancer." (PMID 36831112, 2023). "We also found that NK cells from lung cancer patients had lower expression of CD226 on their surface and exhibited a pro-inflammatory, pro-angiogenic and tumorigenesis phenotype by expressing VEGF, CXCL1, CXCL8, S100A8 and MMPs." (PMID 34944871, 2021). "CXCL8 is one of the most studied members of the CXC (ELR+) family, particularly in lung cancer." (PMID 21298036, 2011). "Moreover, ILC1s themselves have been shown to secrete vascular endothelial growth factor (VEGF), CXCL8/IL-8, and matrix metalloproteinases (MMPs) in several cancer types, including HCC, CRC, and lung cancer, further promoting angiogenesis and tumor progression." (PMID 40963622, 2025).